NSUN2 (NOP2/Sun RNA methyltransferase 2)
Description:
RNA cytosine C(5)-methyltransferase that methylates cytosine to 5-methylcytosine (m5C) in various RNAs, such as tRNAs, mRNAs and some long non-coding RNAs (lncRNAs). Involved in various processes, such as epidermal stem cell differentiation, testis differentiation and maternal to zygotic transition during early development: acts by increasing protein synthesis; cytosine C(5)-methylation promoting tRNA stability and preventing mRNA decay. Methylates cytosine to 5-methylcytosine (m5C) at positions 34 and 48 of intron-containing tRNA(Leu)(CAA) precursors, and at positions 48, 49 and 50 of tRNA(Gly)(GCC) precursors. tRNA methylation is required generation of RNA fragments derived from tRNAs (tRFs). Also mediates C(5)-methylation of mitochondrial tRNAs. Catalyzes cytosine C(5)-methylation of mRNAs, leading to stabilize them and prevent mRNA decay: mRNA stabilization involves YBX1 that specifically recognizes and binds m5C-modified transcripts. Cytosine C(5)-methylation of mRNAs also regulates mRNA export: methylated transcripts are specifically recognized by THOC4/ALYREF, which mediates mRNA nucleo-cytoplasmic shuttling. Also mediates cytosine C(5)-methylation of non-coding RNAs, such as vault RNAs (vtRNAs), promoting their processing into regulatory small RNAs. Cytosine C(5)- methylation of vtRNA VTRNA1.1 promotes its processing into small-vault RNA4 (svRNA4) and regulates epidermal differentiation. May act downstream of Myc to regulate epidermal cell growth and proliferation (By similarity). Required for proper spindle assembly and chromosome segregation, independently of its methyltransferase activity.
Synonyms: Misu; SAKI; TRM4; FLJ20303; MRT5
Tractability: Antibody: UniProt places it where antibodies can reach, with medium confidence; its Gene Ontology location is reachable by antibodies, with medium confidence. PROTAC: UniProt records ubiquitination sites on it; ubiquitination databases record sites on it; its protein half-life has been measured.
Target class: Enzyme; Transferase
Gene: Protein-coding gene on chromosome 5 (6,599,237 to 6,633,304, reverse strand). Ensembl gene ENSG00000037474.
Subcellular location: Nucleus, nucleolus; Cytoplasm; Mitochondrion; Cytoplasm, cytoskeleton, spindle; Secreted, extracellular exosome
Subcellular location (Human Protein Atlas): Nucleoplasm
Pathways (Reactome):
Metabolism of RNA: tRNA modification in the nucleus and cytosol
Gene Ontology:
Molecular function: mRNA (cytidine-5-)-methyltransferase activity; protein binding; RNA binding; tRNA (cytidine-5-)-methyltransferase activity; tRNA binding; methyltransferase activity; RNA methyltransferase activity; S-adenosylmethionine-dependent methyltransferase activity
Biological process: mRNA processing; regulation of mRNA export from nucleus; tRNA methylation; hair follicle maturation; regulation of stem cell differentiation; tRNA modification; tRNA stabilization
Cellular component: cytoplasm; extracellular exosome; mitochondrion; nucleolus; nucleoplasm; nucleus; extracellular region; spindle
Genetic constraint (gnomAD): Loss-of-function variants: 55 observed, 71.33 expected, observed/expected ratio (o/e) 0.77, 90% interval 0.62 to 0.96. The upper end of that interval is the gene's LOEUF score, 0.96, which puts it in group 4 of 6, group 1 being the genes least tolerant of losing a copy. Missense variants: 860 observed, 871.83 expected, observed/expected ratio (o/e) 0.99, 90% interval 0.93 to 1.04. Synonymous variants: 320 observed, 319.12 expected, observed/expected ratio (o/e) 1, 90% interval 0.91 to 1.1.
Gene-disease validity (ClinGen):
ClinGen rates the evidence that NSUN2 causes each of these diseases.
syndromic intellectual disability (autosomal recessive): Definitive. A intellectual disability that is part of a larger syndrome.
RASopathy (autosomal recessive): Disputed. Developmental syndromes caused by germline mutations (or in rare cases by somatic mosaicism) in genes that alter the Ras subfamily and mitogen-activated protein kinases that control signal transduction.
Homologues: Orthologues: chimpanzee NSUN2 (99% identical), macaque NSUN2 (98% identical), mouse Nsun2 (87% identical), dog NSUN2 (86% identical), rat Nsun2 (86% identical), pig NSUN2 (85% identical), guinea pig NSUN2 (85% identical), rabbit NSUN2 (76% identical), tropical clawed frog nsun2 (71% identical), zebrafish nsun2 (69% identical), Drosophila melanogaster Nsun2 (42% identical). Paralogues in human: NSUN4 (11% identical), NSUN3 (10% identical).
Diseases named in the same sentence as NSUN2 in open-access papers:
NSUN2 is named in the same sentence as 138 diseases in open-access papers, as found by Europe PMC text mining. Sharing a sentence is not in itself a finding about the gene and the disease. The quoted sentences say what the papers report.
gastric cancer (58 papers, 2020 to 2026). A primary or metastatic malignant neoplasm involving the stomach. "Research indicates that NSUN2 is upregulated in gastric cancer and is significantly associated with lower survival rates in patients." (PMID 40370440, 2025). "The m5C methyltransferase NSUN2 is overexpressed in gastric cancer tissues and is linked to lymphatic metastasis and higher Ki67 expression." (PMID 41584846, 2025). "In gastric cancer, NSUN2 overexpression has been shown associated with metastasis and regulated by SUMO-2/3 that stabilized and mediated its transport into the nucleus." (PMID 37369946, 2023). "Similarly, M5C methyltransferase NSUN2 is overexpressed in gastric cancer and can be used as a risk factor for the overall survival of gastric cancer patients." (PMID 37228500, 2023). "Notably, the mutation frequencies of NSUN2 in esophagus and stomach cancers, NSUN3 in esophagus cancer, and ALYREF in liver cancer were particularly high." (PMID 33365328, 2020). "Studies show that during the peritoneal metastasis of gastric cancer, NSUN2 expression significantly increases, correlating strongly with metastatic advancement." (PMID 39791162, 2025). "We first analyzed the protein levels of NSUN2 and GCLC in six gastric cancer cell lines by western blotting analysis, and found a relatively higher level of NSUN2 in all cell lines, except SNU-1." (PMID 39742570, 2025). "NSUN2 K508la upregulates glutathione levels in gastric cancer, enhancing the resistance to ferroptosis-inducing agents such as doxorubicin and RSL3." (PMID 40994548, 2025). "Silencing NOP2/Sun RNA methyltransferase family member 2 (NSUN2) effectively inhibits gastric cancer (GC) progression but is limited by RNase degradation, rapid renal clearance, and low uptake." (PMID 40444266, 2025). "In our previous study, we discovered that NSUN2 contributes to the progression of gastric cancer via both m5C‐dependent and m5C‐independent pathways." (PMID 40156167, 2025). "In gastric cancer (GC), NSUN2 mediates tumor cell survival in acidic microenvironments through lactate-induced lysine lactylation." (PMID 41256859, 2025). "Accumulating evidence has shown that NSUN2-mediated mRNA m5C modification plays a vital role in various cancers, such as gastric cancer, oesophageal squamous cell carcinoma, and bladder cancer." (PMID 39924557, 2025). "We further demonstrated that GCLC mRNA is a target of lactylated NSUN2, which coordinately regulates the lipid peroxidation level and the phenotype to ferroptosis resistance in gastric cancer cells." (PMID 39742570, 2025). "We initially observed this phenomenon in gastric cancer, where m5C enzymatic‐dead mutants of NSUN2 (C271A and C321A) partially promoted the proliferation and metastasis of gastric cancer cells." (PMID 40156167, 2025). "In vitro and in vivo experiments confirm that NSUN2 promotes gastric cancer cell proliferation and tumor development." (PMID 40370440, 2025). "Strikingly, similar to our previous study on gastric cancer cells, we found that overexpression of both the wild‐type and enzymatic‐dead mutant NSUN2 in HCT116 cells enhanced their proliferation and metastatic abilities." (PMID 40156167, 2025). "In gastric cancer (GC), NSUN2 promotes cell proliferation and metastasis, with similar pro-tumorigenic effects observed in other malignancies, including hypopharyngeal squamous cell carcinoma and prostate cancer." (PMID 41463199, 2025). "DIAPH2‐AS1, a lncRNA upregulated in neural invasion‐positive gastric cancer, enhances NSUN2 stability by shielding it from ubiquitin‐proteasomal degradation at specific lysine residues." (PMID 39377984, 2024). "For example, one study found that NSUN2 was upregulated in gastric cancer (GCs), and by targeting PIK3R1 and PCYT1A, NSUN2 promoted the proliferation of GCs." (PMID 38572667, 2024).
gastric cancer (continued). "SUMOylation is a significant regulatory posttranslational modification, and its covalent bond interaction with NSUN2 to form the SUMOylation–NSUN2–m5C axis is a novel mechanism and therapeutic target for gastric cancer cells." (PMID 39006762, 2024). "Recent researches indicate that SUMO-2/3 modification of the RNA methyltransferase NSUN2 enhances the onset and progression of gastric cancer." (PMID 37670275, 2023). "Cell experiments demonstrated that NSUN2 promoted gastric cancer cell proliferation, migration, and invasion." (PMID 37228500, 2023). "By increasing m5C levels, NSUN2 encourages gastric cancer (GC) cells to proliferate, migrate, and invade." (PMID 37751592, 2023). "NSUN2 is highly expressed in multiple tumor types, such as gastric cancer and esophageal squamous cell carcinoma." (PMID 36183976, 2023). "Consistent with our findings, it has been reported that NSUN2 is involved in the development of gastric cancer, esophageal squamous cell carcinoma (ESCC), gallbladder carcinoma and other human cancers." (PMID 37393317, 2023). "For example, the m5C methyltransferase NSUN2 promotes the proliferation, migration, and invasion of gastric cancer cells." (PMID 37398932, 2023). "Accumulated evidence has demonstrated that NSUN2 is overexpressed in various tumors such as low-grade glioma, gastric cancer, triple-negative breast cancer, and so on." (PMID 35574373, 2022). "The m5C methyltransferase NSUN2 is significantly upregulated in gastric cancer and is predictive of a poor prognosis in gastric cancer patients." (PMID 35833147, 2022). "SUMO-2/3-modified NSUN2 reportedly promotes the progression of gastric cancer by regulating m5C mRNA methylation." (PMID 36532062, 2022). "A recent study found in gastric cancer found that high NSUN2 levels were associated with worse overall survival, and that knockdown of Nsun2 resulted in decreased proliferation in gastric cancer cells." (PMID 35350378, 2022). "Recently, NSUN2 was reported to promote gastric cancer cell proliferation in a m5C-dependent manner." (PMID 34926580, 2021). "Meanwhile, to determine NSUN2 expression in gastric cancer tissues, we examined expression of NSUN2 in gastric cancer patients’ tissues by performing quantitative real-time PCR (qRT-PCR) and western blot assay." (PMID 32332707, 2020). "Subsequent RNA-seq and KEGG analysis found that cell cycle was the main pathway regulated by NSUN2 in gastric cancer." (PMID 32332707, 2020). "To identify the downstream targets regulated by NSUN2 in gastric cancer, we performed RNA-Seq assay to determine the mRNA expression changes in NSUN2 knockdown and corresponding wild-type cells." (PMID 32332707, 2020). "Our study showed that NSUN2 was significantly upregulated in gastric cancers, compared to adjacent normal gastric tissues." (PMID 32332707, 2020). "In the present study, we firstly showed that NSUN2 was significantly upregulated in gastric cancers, compared to adjacent normal gastric tissues." (PMID 32332707, 2020). "In our study, we found that the expression level of NSUN2 was negatively correlated with p57Kip2 and the ability of NSUN2 knockdown cells proliferation was enhanced after p57Kip2 silencing in gastric cancer." (PMID 32332707, 2020). "It revealed another regulatory mechanism that NSUN2 play an oncogenic role by repressing p57Kip2 expression in gastric cancer." (PMID 32332707, 2020). "In this study, we found NSUN2 was upregulated in gastric cancer tissues, compared to adjacent normal gastric tissues in mRNA and protein levels." (PMID 32332707, 2020). "Further study demonstrated that p57Kip2 was the potential downstream gene regulated by NSUN2 in gastric cancer." (PMID 32332707, 2020). "Further study demonstrated that CDKN1C (p57Kip2) was the potential downstream gene of regulated by NSUN2 in gastric cancer." (PMID 32332707, 2020).
gastric cancer (continued). "In addition, endogenous NSUN2 was also observed to be lactylated with an enhanced level under lactate treatment in MKN45 gastric cancer cells." (PMID 39742570, 2025). "NSUN2 K508la augments glutathione synthesis, suppressing ferroptosis in gastric cancer cells." (PMID 40994548, 2025). "Additionally, in the case of tumor suppressor genes, NSUN2 also decrease the mRNA stability of p57Kip2 through m5C modification, thereby facilitating the progression of gastric cancer." (PMID 41463199, 2025). "For instance, the methylase NSUN2 exhibits significantly higher expression in gastric cancer tissues than non-cancerous tissues, potentially suppressing the expression of p57Kip2 and promoting gastric cancer cell proliferation." (PMID 39164641, 2024). "These insights suggest that modulating NSUN2's SUMOylation could offer new therapeutic avenues for gastric cancer." (PMID 39377984, 2024). "In addition, NSUN2 is upregulated in gastric cancer and promotes cancer cell proliferation, migration and invasion." (PMID 39006762, 2024). "Enhanced levels of NSUN2 and NSUN2-mediated m5C are observed in patients with gastric cancer (GC), esophageal squamous cell carcinoma (ESCC), hepatocellular carcinoma (HCC), hypopharyngeal squamous cell carcinoma (HPSCC), prostate cancer, cervical cancer, nasopharyngeal carcinoma and uveal melanoma." (PMID 37325635, 2023). "PIK3R1 and PCYT1A expression correlated with prognosis and NSUN2 expression, and they could be the target genes that participate in gastric cancer progression." (PMID 37369946, 2023). "Moreover, NSUN2 fuels gastric cancer cell proliferation by repressing CDKN1C in an m5C‐dependent manner." (PMID 37228185, 2023). "Notably, NSUN2-KO cells inhibit the expression of FZR1 in gastric cancer cells, which is consistent with HCC." (PMID 35562754, 2022). "Besides, NSUN2 promoted the proliferation and metastasis of tumor cells and the progression of gastric cancer and breast cancer." (PMID 36118897, 2022). "In vitro, NSUN2 promotes the proliferation, migration, and invasion of gastric cancer cells." (PMID 35833147, 2022). "In addition, there have been reports that NSUN2 is significantly up‐regulated in gastric cancer, inhibits the expression of CDKN1C in an m5C‐dependent manner and promotes the proliferation of gastric cancer cells." (PMID 33400376, 2021). "Post-translational regulation of NSUN2 may be one of the important reasons, which may be different in various gastric cancer cases." (PMID 32332707, 2020). "In the present study, we explored the effects of NSUN2 on gastric cancer cell cycle progression and demonstrated that NSUN2 could repress p57Kip2 by an m5C-dependent manner." (PMID 32332707, 2020). "This study suggested that NSUN2-mediated m5C methylation of p57Kip2 mRNA may serve as novel mechanism for gastric cancer development and progression." (PMID 32332707, 2020). "NSUN2 could promote gastric cancer cell proliferation through repressing p57Kip2 in an m5C-dependent manner." (PMID 32332707, 2020). "We also found NSUN2 could increase gastric cancer cells proliferation both in vitro and in vivo significantly." (PMID 32332707, 2020). "Although p57Kip2 might not be the only targeted gene of NSUN2, our results confirmed that p57Kip2 was an important downstream gene regulated by NSUN2 in gastric cancer." (PMID 32332707, 2020). "Taken together, our results suggested that NSUN2 could promote the gastric cancer cell proliferation in vitro." (PMID 32332707, 2020). "Additionally, SUMO-2/3 has been shown to stabilize NSUN2 and facilitate its nuclear transport in gastric cancer 48, while glucose-induced oligomerization and activation of NSUN2 promote TREX2 expression, suppressing cGAS/STING activation to regulate oncogenic activity in cancer cells." (PMID 41356184, 2026).